DES (desmin)
Diseases named in the same sentence as DES in open-access papers (continued):
Sharing a sentence is not in itself a finding about the gene and the disease.
myopathies (continued). "Moreover, mitochondrial abnormalities, including the loss of proper morphology, swelling, and the loss of cristae structure were detected in desL114F/L114F mice, which are compatible with a common pathological feature among desmin-related myopathies." (PMID 31835587, 2019). "In various subsequent age-related studies applying this set of SHG morphometry tools to dystrophic mdx or R349P mutant desmin muscle, we established these morphometric parameters for structural diagnosis of ‘myopathy’ and for monitoring disease progression with age24–27." (PMID 30374401, 2018). "The role of oxidation in desmin-related myopathies is also highlighted by the fact that a myopathy once classified as MFM based on desmin aggregation, selenoprotein 1-related myopathy, was found to be caused by mutations in SEPN1, which is involved in oxidative homeostasis." (PMID 30289745, 2018). "In the context of myofibrillar myopathies, mitochondrial pathology has been reported in patients with mutations in filamin-C, myotilin, ZASP, FHL1, plectin, and desmin." (PMID 27393313, 2016). "The appearance of desmin aggregates is characteristic of myofibrillar myopathies." (PMID 26333167, 2015). "Together, these results demonstrate that clinically useful pharmaceutical products can be combined to reduce desmin aggregation, which could reduce the cellular burden in myofibrillar myopathies." (PMID 26333167, 2015). "In addition, BAG3 protein co-localized with sites of desmin aggregation found in skeletal muscle from canine myofibrillar myopathy." (PMID 21423662, 2011). "The data suggest that the interaction of αB-crystallin with desmin filaments does not always lead to the prevention of desmin filament aggregation, which we discuss with respect to desmin filament aggregation as a histopathological characteristic of desmin related myopathies." (PMID 22096479, 2011). "Desmin may be a useful promoter to incorporate when performing systemic transgene delivery in myopathies." (PMID 18811960, 2008). "Moreover, our study emphasizes that mitochondria can be considered as a promising therapeutic tool to treat MFM1 myopathy not solely in cardiac muscle but also in all the organs affected by desmin mutations." (PMID 38167524, 2024). "Whether loss of intact desmin filaments in skeletal muscle, as occurs in desmin myopathies, affects DGC integrity or signal transmission via the insulin receptor, and whether plakoglobin cellular distribution changes in these diseases are important questions for future research." (PMID 32170063, 2020). "Interestingly, Desmin is upregulated in all three inflammatory myopathies." (PMID 23071619, 2012). "The reported pathological features in all HSPB8-related myopathies have been similar: dystrophic changes and MFM pathology with protein aggregates (desmin, myotilin, CRYAB, dystrophin, HSPB8, DNAJB6, myotilin, BAG3, TDP-43, and ubiquitin) and rimmed vacuoles." (PMID 32093037, 2020). "Both disorganization and aggregates of desmin have previously been described in several myopathies, but to our knowledge, no disease has been related to the absence of desmin and its mRNA in muscle fibers." (PMID 38566246, 2024). "Muscle fibres containing disorganized or disrupted desmin have been described in several myopathies, but no disease or neuromuscular injuries have been related to lack of desmin in muscle fibres." (PMID 30764835, 2019). "All showed no apparent symptoms or clinical signs indicative of desmin-related myopathy." (PMID 40606663, 2025). "In line with human patients with HSPB8-related myopathy, the muscle pathology shows features of human myofibrillar myopathy, with Z-disc disintegration, accumulation of granulofilamentous material, aggregates positive for HSPB8, CRYAB, and desmin, and rimmed vacuoles." (PMID 32093037, 2020). "Furthermore, despite the absence of desmin, EOMs remain unaffected in desmin-related myopathy." (PMID 38732204, 2024).
cancer (67 papers, 2004 to 2025). A tumor composed of atypical neoplastic, often pleomorphic cells that invade other tissues. "In the TME of pancreatic cancer, there is a positive correlation between PAK1 expression and the expression of α-SMA and Desmin, suggesting the potential involvement of cancer-associated fibroblasts (CAFs), which are known contributors to angiogenesis." (PMID 38067120, 2023). "Consistently, numerous studies demonstrated a preferential loss of Desmin in surrounding cells to dysplastic (precancerous) sites and carcinoma." (PMID 27876887, 2016). "These cell populations were further analyzed by using Lamp1PM expression in combination with a set of canonical markers distinct for cancer and stromal cells (i.e., desmin, Ki67, Sca1, Sma, Pcam1, CD44, Lyve1, and EpCam)." (PMID 36127469, 2022). "While genes such as PTH1R, DPT, DES, TCF21 and PDE2A are downregulated in many cancers, cell cycle associated genes, centromere proteins and kinesin family proteins are upregulated in all the cancer types we studied." (PMID 34728699, 2021). "The role of PRPH in cancer is less clear: it encodes the cytoskeletal protein peripherin, a type III intermediate filament with homology to other cytoskeletal proteins such as desmin, and that is found in neurons of the peripheral nervous system." (PMID 32441866, 2020). "Besides the general roles of neural stemness genes in promoting cancer, expression of Acta2, Desmin or Kdr is frequently observed during cancer progression, and Afp is used as a marker for cancers of the liver, testicles and ovaries." (PMID 33468253, 2021). "Therefore, we can propose that each isoform of DeS enzyme has a distinctive action that requires further investigation to explore their roles in cancer resistance." (PMID 34637456, 2021). "On the other hand, we examined the expression of the mesenchymal markers desmin and vimentin and found that the levels of both proteins were suppressed in the BNE-RRC-treated cancer cells, indicating the loss of MET in these cancer cells under the treatment with BNE-RRC." (PMID 39273519, 2024). "And most of the 24 DEPs (CDK1, SFN, PRKAR2B, MKI67 and MDK involved in the cell cycle; LOXL2, P4HA1, P4HA2, SPRX, DES, PRPH and CALML3 involved in construction and regulation of extracellular matrix; IL33 and EHD3 may involve in immune) were linked to cancer hallmarks." (PMID 33200655, 2020). "Detection of differential markers subtyped the cells of mesenchymal origin (vimentin, desmin, cadherin-11, podoplanin, CD74, S100A4, CD44, FAP), which vary according to the functional differentiation and specialization in sites of cancer tissue." (PMID 39575252, 2024). "As expected, most up-regulated proteins are related to cancer genes, with seven of them known to be enhanced in PCa (SYNM, DES, MYH11, TAGLN, CNN1, LMOD1, and PGM5)." (PMID 38052461, 2024). "A contrasting pattern of similarity emerges among carcinomas originating from uterine, pulmonary, and hepatic tissues, where genes like CTHRC1, ADH1B, GHR, DES, SFRP1, and RNF150 share similar weights." (PMID 39596491, 2024). "The study reported that the potential muscle-specific genes expressed in cancer cells were TNNI1, TNNT1, DES, TRDN, MYH6, MYH11, and MYH13." (PMID 36378654, 2022). "We first examined E6AP and desmin, a marker of HSC activation in the cirrhotic and adjacent normal tissue samples from patients with cancer to find the biological significance of E6AP in a clinical situation." (PMID 31949242, 2020). "A few genes were found to be in both the cancer grading and staging signatures, such as CPS1, DES, GFRA3, TMED6 and DPT, indicating some biological relevance between cancer differentiation and progression." (PMID 21445269, 2011). "The cytokeratins belong to the type I and II of the IF's, desmin and vimentin belong to the type III and lamin to type V. This group of proteins have been widely used as markers of different cancers." (PMID 21711556, 2011).
cancer (continued). "In addition to its anti-cancer properties, BNE-RRC can reverse the EMT in cancer cells by suppressing mesenchymal markers, such as desmin and vimentin, and increasing the expression of the MET marker α-catenin." (PMID 39273519, 2024). "Immunohistochemical (IHC) analysis revealed that the cancer cells were negative for desmin and positive for vimentin." (PMID 38185762, 2024). "These cancer cells were negative for desmin, but positive for vimentin, CK7, and CK19 on immunohistochemical examination." (PMID 38185762, 2024). "The immune histochemical sections of the HPA database showed that the protein expression of SLPI, DES, IAPP, NPY, ISG15 and HLA-DMB in normal tissue was higher than that in cancer tissue, while the protein expression of PLA2G2A in normal tissue was lower than that in cancer tissue." (PMID 36774376, 2023). "We performed immunostaining for transcription factor E3 (TFE3), human melanoma black 45 (HMB45), melan-A, desmin, pan-cytokeratin (CK), paired box 8 (PAX8), CD10, hormone receptors, and S100, and targeted RNA and DNA sequencing using commercially available cancer gene panel." (PMID 35626258, 2022). "However, none of these markers are specific for myofibroblasts: FSP1 is also expressed in macrophages and cancer cells, FAP is expressed in some immune cells, and desmin and PDGFRβ are in perivascular cells." (PMID 36542704, 2022). "In contrast, Jag1 was detected in desmin-positive HSCs present in area #2, but not in cancer cells in both areas." (PMID 35064244, 2022). "Elongated Cav-1 positive but Desmin negative cells (non muscle cells) were however observed and such areas were generally SMA positive suggesting that some myofibroblasts (cancer associated fibroblasts, CAFs) express Cav-1." (PMID 27764093, 2016). "Immunohistochemistry revealed that cancer cells were positive for cytokeratins and vimentin to a varying degree and negative for Desmin, S-100, Osteopontin, BMP-2 or BMP-4." (PMID 19040765, 2008). "Interestingly, PDGFR+/desmin+ pericytes, but not PDGFR+/CD13+, have been associated with the metastasis and proliferation of cancer cells." (PMID 36835266, 2023). "The first three genes most correlated to cancer in the colon dataset were heavy chain of non-muscle myosin, human monocyte-derived neutrophil-activating protein (MONAP) and human desmin genes." (PMID 15469618, 2004). "Furthermore, cancer cells produce several growth factors, such as PDGF-B, VEGFA, and TGF-β1, which may trigger the prevalence of a PDGFR+/desmin+ pericyte phenotype and not the PDGFR+/CD13+ phenotype." (PMID 36835266, 2023).
cardiac disease (23 papers, 2014 to 2026). "As a consequence, variations in the desmin (DES) gene have been reported in a number of cardiac diseases including atrial and ventricular arrhythmias, as well as hypertrophic-, restrictive-, dilated-, and non-compaction cardiomyopathy." (PMID 36158202, 2022). "In the setting of heart disease, the increased abundance of both desmin intermediate filaments and detyrosinated microtubules thus promotes a feed-forward substrate for enhanced mechanotransduction and myocardial stiffening." (PMID 36326891, 2022). "The intracellular stiffness factors desmin and α-actinin are additional players in cardiac diseases." (PMID 33718383, 2021). "Because cytoplasmic aggregates of desmin and αB-crystallin were documented in human cardiac patients and rodent models of heart disease we sought to examine the cellular localisation of desmin and αB-crystallin and assess their spatial relationship using immunohistofluorescence in feline hearts." (PMID 40658643, 2025). "Different genes have been found to be related to ALVC, and the more frequent are Desmoplakin (DSP), Filamin C (FLNC), Phospholamban (PLN), and Desmin (DES); however, there is a prevalence of variants of genes already known to be related to inherited cardiac disease and of gene-elusive cases." (PMID 35893404, 2022). "During cardiac diseases, desmin is modified by phosphorylation or in expression levels." (PMID 33718383, 2021). "The inadequate upregulation of Nkx2.5 expression in desmin null stem cells after injury or stress might contribute to a compromised regenerative potential in desmin-related heart diseases." (PMID 26787680, 2016). "Our findings uncover a CK2α-Desmin-mitochondrial quality control axis as a critical metabolic-structural checkpoint in cardiomyocytes and establish that cardiomyocyte-initiated paracrine signaling drives fibroblast activation, highlighting new therapeutic strategies for fibrotic heart disease." (PMID 42095508, 2026). "In general, the accumulation of cytoskeletal proteins such as tubulin, desmin, and membrane associated proteins might be the compensatory mechanism of heart malfunction independent of the fundamental cardiac disease." (PMID 35837601, 2022). "Therefore, both overexpression and absence of Desmin have been linked to cardiac diseases." (PMID 37428366, 2023). "Furthermore, mutations in non-desmosomal genes, including Transmembrane protein 43—luma (TMEM 43), Phospholamban (PLN), Filamin C (FLNC), Desmin (DES), and LMNA (Lamin A/C), have been identified as contributing to the pathogenesis of heart disease." (PMID 40361967, 2025). "This may explain the observation that desmin is considerably affected in the skeletal muscle while it is not in the cardiac muscle since the patient does not show clinical manifestations of heart disease." (PMID 35720129, 2022). "Indeed, the upregulation of desmin expression in the early stages of any cardiac disease may be assumed to be a compensatory process because no immunohistochemical features of desmin expression disarray are observed in these groups." (PMID 37834000, 2023).
infection (13 papers, 2013 to 2025). The state of being infected such as from the introduction of a foreign agent such as serum, vaccine, antigenic substance or organism. "Similarly, desmin, a gene associated with myogenesis, was undetectable, and the adipogenesis-related genes examined in this study remained unchanged following infection." (PMID 39467689, 2024). "In addition, it has been reported that desmin and vimentin are associated with the infection of TMEV, a neurotropic murine picornavirus." (PMID 36851648, 2023). "Here, we examined the entire dC2C12 culture, at 20 days post-infection, through serial scans along the z-axis with double staining immunocytochemistry for the prion protein and desmin, a major intermediate filament protein present in muscle-derived cells." (PMID 38139358, 2023). "On the contrary, transfection of miR-21 mimics, knocking down of YOD1 or infection of CVB3 induced more cytoplasmic distribution of desmin than the controls." (PMID 24722419, 2014). "Nuclear NP immunoreactivity was first detected in desmin-positive, multinucleated, differentiated myotubes at 4 hours post-infection (hPI) with the seasonal virus A/Paris/1149/2008, and between 4 and 6 hPI with the pandemic virus A/California/7/2009." (PMID 24223983, 2013). "However, the level of desmin, a marker for activated and transdifferentiated HSCs, increased after infection in all age groups." (PMID 39404406, 2024). "In addition, we found that desmin functions as a positive regulator during the RABV infection; while the overexpression of desmin increased the virus yield, the suppression of endogenous desmin inhibited the virus release." (PMID 36851648, 2023). "Interestingly, while the virion yield showed a step-by-step increase along with the infection time from the control cells, the knockdown of the endogenous desmin substantially impaired the virus release." (PMID 36851648, 2023). "On the contrary, after MyoD lentiviral infection and 10 days of transdifferentiation (5 days in primary differentiation medium and 5 days in secondary differentiation medium), fibroblasts express the two skeletal muscle markers, desmin and MF20 (respectively)." (PMID 37265839, 2023). "Western blot analysis further demonstrated increased protein levels of YAP and HSC activation markers (Desmin and α-SMA) following infection, while phosphorylated YAP (p-YAP) expression was reduced." (PMID 41220567, 2025). "The BHK-21 cells were transfected with the random siRNA control or the desmin-specific siRNAs, followed by the RABV (RC-HL strain) infection at an MOI of 0.1." (PMID 36851648, 2023). "As the infection with S. mansoni induced hepatic desmin but not αSMA, we aimed to analyze whether S. mansoni eggs directly stimulate alternative HSC activation without an immune reaction against the parasite." (PMID 39404406, 2024). "We found that the exogenous expression of desmin modestly enhanced the RABV-N and RABV-M mRNA expression levels at 24 h post infection, but did not alter the viral protein expression levels." (PMID 36851648, 2023).
adenocarcinoma (5 papers, 2014 to 2023). A common cancer characterized by the presence of malignant glandular cells. "However, in human brain metastases, desmin expression was inconclusive in adenocarcinoma and carcinoma brain metastases." (PMID 31695842, 2019).
renal disease (5 papers, 2012 to 2024). "Accumulating evidences have suggested that podocytes undergo ferroptosis in progressive kidney disease, which expressed as loss of epithelial markers, such as synaptopodin, together with gaining mesenchymal features (desmin)." (PMID 37819479, 2023).
neuromuscular disease (4 papers, 2008 to 2022). "With a mean age of the onset of the first neuromuscular symptoms of 35 years, patients suffering from a mutation in desmin often present fairly late in life compared to other inheritable neuromuscular diseases." (PMID 32893996, 2020). "Desmin, also a type-III IF protein found mainly in smooth and cardiac muscle cells, has been the subject of extensive study in desmin-related myopathy (DRM), an adult-onset neuromuscular disease characterized by large accumulations of aggregates of cytoplasmic desmin and R120G mutant αB-crystallin." (PMID 18618007, 2008).
genetic diseases (2 papers, 2024 to 2025). "Desmin-related myofibrillar myopathy is a group of genetic diseases with similar pathological changes in muscle tissue, caused by mutations in the desmin gene." (PMID 40007819, 2024). "Loss of vimentin or desmin leads to mitochondrial dysfunction and increased oxidative stress in various models, worsening the progression of genetic diseases such as those caused by desmin and glial fibrillary acidic protein (GFAP) mutations, which amplify oxidative damage." (PMID 41465278, 2025).
mitochondrial disease (1 paper, 2023). "Reciprocally, several pathophysiological situations including hypoxia, inflammation, and mitochondrial diseases can lead to oxidative stress, eliciting desmin modifications and potentially misfolding." (PMID 37760006, 2023). "Interestingly, desmin has been identified as one of the proteins nitrated in tyrosine in muscle biopsies from patients with mitochondrial diseases (mitochondrial respiratory chain dysfunction of various origins)." (PMID 37760006, 2023).
skeletal diseases (1 paper, 2023). "The shortage of desmin has been proven to be a critical pathogen in cardiac and skeletal diseases 36-38." (PMID 37324935, 2023).
DES also shares sentences with these, for which no sentence is quoted: solitary fibrous tumor (8 papers); malignant fibrous histiocytoma (4); endometrial stromal sarcoma (3); endometriosis (3); hamartoma (3); lipoma (3); prostate carcinoma (3); proteinopathy (3); restrictive cardiomyopathy (3); squamous cell carcinoma (3); amyloidosis (2); cardiac arrhythmia (2); cholestasis (2); filaminopathy (2); idiopathic dilated cardiomyopathy (2); left ventricular non-compaction cardiomyopathy (2); leukemia (2); limb-girdle muscular dystrophies (2); liver disease (2); metastasis (2); myxoid liposarcoma (2); nephrosis (2); neurodegenerative disease (2); neuroendocrine carcinoma (2); ovarian carcinoma (2); paraganglioma (2); pleomorphic rhabdomyosarcoma (2); small bowel tumor (2); viral myocarditis (2); acute myocardial infarction (1).
A further 137 diseases each share a sentence with DES in 1 paper.